KLF4 (KLF transcription factor 4)
Diseases named in the same sentence as KLF4 in open-access papers (continued):
Sharing a sentence is not in itself a finding about the gene and the disease.
tumor (continued). "PTTG1 marks some specific OCT4- and KLF4-positive tumor cells, mainly localized at the periphery of the neoplasm." (PMID 31572301, 2019). "We found 5 target gene candidates (Skp2, Psme3, Pik3cd, Klf4, and Hoxb5) that were consistently predicted by the three software and involved in tumor-related signaling pathway." (PMID 30967999, 2019). "In oral squamous cell carcinoma, KLF4 showed dual functionality as a tumor suppressor as well as an oncogene." (PMID 31245293, 2019). "The intensity and percentage of KLF4 positive staining was varied in the metastatic tumor tissues located in the trachea and main bronchus." (PMID 31969824, 2019). "Most notably, several studies indicated that miR-7 functioned as tumor suppressor gene via direct regulation of KLF4." (PMID 29614984, 2018). "We observed that A375 (but not BLM) cells are able to form melanospheres and show CSCs traits: expression of the pluripotency markers SOX2 and KLF4, higher invasiveness and tumor formation capability in vivo with respect to parental adherent cells." (PMID 29330434, 2018). "H-Ras and PI3K were common mutations associated with cetuximab resistance, and contrary to our previous research, KLF4 played the role of an tumor suppressor in these processes." (PMID 29973197, 2018). "The previous study found that oncogene Klf4 played a role of tumor suppressor in the nasopharyngeal cytoplasm." (PMID 29973197, 2018). "RT-qPCR demonstrated that primary canine OSA tumor tissues express high levels of putative miR-34a target genes, KLF4 and SEMA3E." (PMID 29293555, 2018). "In the other hand, studies reported that Klf4 as a tumor suppressor plays key roles during the differentiation, proliferation and apoptosis." (PMID 29564063, 2018). "To evaluate how Klf4 influences myeloid composition and macrophage polarization in Hi-Myc tumors, we analyzed a panel of surface markers on dissociated tumor cells by multi-color flow cytometry." (PMID 29324844, 2018). "Previous studies have shown that KLF4 is essential for promoting migration and invasion, resulting in tumor formation in vivo." (PMID 29899271, 2018). "A more recent study demonstrated that during tumor metastatic process, inactivation of KLF4 suppressed pre-metastatic niche formation and metastasis in perivascular cells." (PMID 29789534, 2018). "As a transcription factor, KLF4 positively or negatively regulates its downstream targets after binding a DNA sequence and acts as a tissue-specific tumor suppressor or oncogene during tumorigenesis." (PMID 29789534, 2018). "The expression of PLAC8 in LC was transcriptionally inhibited by KLF4, an important tumor-suppressive transcriptional factor during LC progression." (PMID 29789534, 2018). "The mean fluorescence intensity (MFI) of CD11c, present on activated macrophages, was increased 2-fold in Klf4(f/f);Lys-Cre compared with Klf4(f/f) PCa tumor recipients." (PMID 29324844, 2018). "The frequency of CD8 T cells expressing these markers were markedly increased in Klf4(f/f);Lys-Cre hosts, representing 1.5% or 3% of viable tumor cells." (PMID 29324844, 2018). "Wan and colleagues recently discovered that KLF4 interacts with methylated DNA to activate RhoC expression via chromatin remodeling, in turn promoting GBM adhesion and migration, two hallmark tumor characteristics that make combatting GBM difficult." (PMID 31245170, 2018). "Conversely, accumulating clinical and experimental evidence also demonstrated that KLF4 has a promoting effect in tumor initiation, progression, or metastasis." (PMID 30108202, 2018). "CD45+CD11b+ myeloid cells represented ~20% of live tumor cells isolated on day 21 from Klf4(f/f) and ~29% of Klf4(f/f);Lys-Cre Hi-Myc PCa recipients, p = 0.07 (right)." (PMID 29324844, 2018). "Collectively, we revealed that PLAC8 acts as an oncogene in the malignant progression of LC and a novel KLF4/PLAC8 signaling pathway that regulates tumor cell proliferation and apoptosis." (PMID 29789534, 2018).
tumor (continued). "Krüppel-like factor 4 (KLF4), a zinc-finger trans-cription factor, functions as a tumor suppressor or an oncogene." (PMID 28978114, 2017). "Histological examination identified an average of 31.4±12.7 and 6.33±3.31 metastatic tumor nodules on lung surface in mice received Klf4-depleted and control transplants, respectively." (PMID 29212199, 2017). "Our findings demonstrate, for the first time, that Klf4, as a tumor suppressor, reduces stemness phenotype, inhibits EMT, and prevents tumor progression in NPC." (PMID 29212199, 2017). "By inhibiting Kruppel-like factor 4 (Klf4), miR-152 is reported to be a tumor suppressor in human GSCs." (PMID 28187439, 2017). "KLF4 is a cell proliferation inhibitor and can act as a tumor suppressor, being normally downregulated in ApcMin/+ tumors and in early stages of human CRC." (PMID 28086833, 2017). "Kruppel like factor 4 (KLF4), a transcription factor associated with carcinogenesis and tumor progression, has opposite effects and mechanisms in different malignancies." (PMID 29254226, 2017). "Subsequently, we further examined the ability of NPC cells to form tumor spheres after Klf4 overexpression or Klf4 silencing by RNAi." (PMID 29212199, 2017). "Bmi1 and Klf4 were negatively related to aggressive tumor characteristics and highly expressed in hormone receptor-positive tumors – the opposite findings to those for Oct4 and Sox2." (PMID 28422735, 2017). "The T classification data from the human NPC biopsies of this study and previous study evidently revealed that Klf4 is significantly downregulated in larger sized tumors, indicating the tumor-suppressive role of Klf4 in NPC, as confirmed by this study." (PMID 29212199, 2017). "KLF4 is a transcription factor with known functions in pluripotency, tumour suppression or progression and cell differentiation." (PMID 28959019, 2017). "Accumulating clinical, experimental and mechanistic evidence suggests that KLF4 functions as a tumor suppressor in various types of cancer, including HCC." (PMID 28978114, 2017). "In GC, the function of KLF4 has been characterized as tumor suppressor and serves as a prognostic predictor for the survival of patients." (PMID 28445396, 2017). "The role of KLF4 in UBC has been preliminarily explored and associated with tumor progression and early recurrence in a previous study." (PMID 29254226, 2017). "KLF4 play a key tumor suppressor role including regulating cell proliferation, migration and invasion in GC." (PMID 29221147, 2017). "Actually, in xenografted tumors, ectopic expression of Klf4 correlated with smaller tumor size, while Klf4 silencing correlated with larger tumor size." (PMID 29212199, 2017). "The predicted CpG methylation status was identified by BSP, revealing that T24 and UM-UC-3 cells, and tumor tissues, were aberrantly hyper-methylated in CpG islands of the KLF4 promotor region compared with para-tumor normal tissue." (PMID 29254226, 2017). "Increased expression of KLF4 is also evident in prostate CTCs compared with primary tumour specimens in our single-cell RNA-Seq data, while its upregulation is less clear in CTCs from lung xenografts because of limited sample size in that cohort." (PMID 28181495, 2017). "The results also indicated a significant tumor weight difference induced by overexpression of KLF4 (P < 0.05)." (PMID 29254226, 2017). "Immunofluorescence staining in archival NPC specimens revealed that subsets of tumour cells co-expressing high EpCAM and low KLF4 protein levels were also present in NPC patients." (PMID 28959019, 2017). "Oct4, Sox2, Nanog, Bmi1, and Klf4 were expressed in 15.4%, 10.3%, 20.4%, 50.5%, and 17.6% of tumor samples, respectively." (PMID 28422735, 2017). "In conclusion, Klf4 functions as a tumor suppressor in NPC to decrease stemness phenotype, inhibit EMT and prevent tumor progression." (PMID 29212199, 2017).
tumor (continued). "In particular, the KLF4 gene contributes to maintaining CSCs and promotes migration and invasion, resulting in tumor formation in vivo." (PMID 27863437, 2016). "Further, mRNA and protein expression analysis of tumor samples also express the markers for stemness like klf4, oct3/4, CD44 and nanog as well as the differentiation marker α-fetoprotein." (PMID 26873175, 2016). "We demonstrate that although KLF4(FL) acts as a tumor-inhibiting gene in MDA-MB-231 cells, an increased KLF4α/KLF4(FL) ratio is able to oppose this effect." (PMID 27323810, 2016). "Our data shed light on the function of KLF4 of inducing cellular senescence in vitro and preventing tumor progression in vivo." (PMID 27531889, 2016). "Second, TICs of any tumor highly express embryonic stem factors, such as Oct-4, Nanog, Sox2, and Klf4." (PMID 26695440, 2016). "KLF4α interacts with KLF4(FL) in the cytoplasm, which prevents nuclear localization of KLF4(FL), thereby inhibiting KLF4(FL) tumor-suppressive functions in the nucleus, such as growth inhibition." (PMID 27323810, 2016). "KLF4 was a complex transcription factor that can act as a transcriptional activator, a transcriptional repressor, an oncogene, and a tumor suppressor." (PMID 27302923, 2016). "It indicated that KLF4 expression and activity are altered in human cancers and KLF4 can be tumor suppressors or oncogenes depending on tissue, tumor type, or cancer stage." (PMID 26823670, 2016). "KLF4 all, KLF4(FL) as well as KLF4α RNA levels were all prominently reduced in the tumor sample compared to control." (PMID 27323810, 2016). "Among 80 patients' tumor tissue samples tested, about 42 patients showed high expression of hTERT and low expression of KLF4 which accounts for 52.5% of all samples." (PMID 27153563, 2016). "There is mounting evidence indicating that KLF4 functions as a tumor suppressor or tumor promoter, depending on the cellular context." (PMID 27835585, 2016). "There is mounting evidence that KLF4 functions as an oncogene or tumor suppressor depending on the tumor type." (PMID 27153563, 2016). "Through immunohistochemistry, we observed that tumor tissues with high miR-1 expression levels exhibited strong cytoplasmic and nuclear staining for KLF4 (left)." (PMID 27991915, 2016). "The zinc finger protein Krüppel-like factor 4 (KLF4) regulates gene transcription and cell fate in a context-dependent manner, and has been shown to promote cell differentiation, and to suppress tumor growth stem cell and malignant progression." (PMID 27102441, 2016). "Conversely, KLF4 over-expression facilitated cell proliferation, colony formation, and cell migration in vitro, and accelerated tumor growth in vivo." (PMID 27105535, 2016). "Augmented KLF4α/KLF4(FL) ratios increased the fraction of cells within S phase and promoted a pro-tumorigenic phenotype by opposing the tumor-suppressive functions of KLF4(FL)." (PMID 27323810, 2016). "Overexpression of KLF4 inhibits cell proliferation in cell lines and suppresses carcinogenesis and tumor metastasis in mice model." (PMID 27531889, 2016). "KLF4 has been reported to have tumor-suppressive functions in various tumors, including tumors of the colon, bladder, prostate, and stomach, while it acts as a pro-tumorigenic gene in oral and skin squamous cell carcinomas." (PMID 27323810, 2016). "The tumor volume and weight of mice with the injection of KLF4 stably knockdown cells were much smaller and lighter compared with control group." (PMID 27105535, 2016). "Here, we established a central role for KLF4 in tumor suppression by connecting its regulation by AR and modulation of miR-1 expression." (PMID 27991915, 2016). "KLF4 is a key regulator of cell proliferation and differentiation and has a tumor suppressor role in many cancers." (PMID 27277677, 2016). "Reduced KLF4 expression was significantly correlated with advanced tumor biology and poor patient survival." (PMID 27057625, 2016).
tumor (continued). "This review focuses on the role of Twist1-Jagged1/Notch-KLF4 axis on tumor-derived endothelial transdifferentiation, tumorigenesis, metastasis, and cancer stemness." (PMID 26823670, 2016). "Most of the tumor samples analyzed in this study displayed a significant increase of the KLF4α/KLF4(FL) ratio compared to controls." (PMID 27323810, 2016). "To investigate the tumor-suppressor role of KLF4, we focused on identifying KLF4 target substrates potentially involved in tumorigenesis prevention." (PMID 27991915, 2016). "Our analysis revealed that a significantly positive correlation exists between PPARγ and KLF4 expression in HCC tissues, suggesting that PPARγ collaborates with KLF4 to facilitate tumor suppression." (PMID 27483249, 2016). "Next, we examined the expression of KLF4 and hTERT in xenograft tumor tissues using immunohistochemical staining." (PMID 27153563, 2016). "Krüppel-like factor 4 (KLF4) is a transcription factor and functions as a tumor suppressor or tumor promoter in different cancer types." (PMID 27531889, 2016). "As an ambiguous cancer-related gene, KLF4 can function as an oncogene or tumor suppressor in specific cellular contexts, although the mechanisms underlying the contribution of KLF4 in malignancies have not been completely established." (PMID 27153563, 2016). "Along with these roles in normal cells and tissues, KLF4 has been reported as a tumor suppressor or an oncogene in many cancers." (PMID 27105535, 2016). "One of the emerging roles of KLF4 is the regulation of diverse tumor progression and its potential prognostic value for patient outcomes as it induces both malignant transformation and a slow-growth phenotype." (PMID 27153563, 2016). "A more recent study shows that micro-RNA targeting of KLF4 suppresses tumor growth in GBM cells but the role of KLF4 in GBM remains undetermined." (PMID 27148537, 2016). "The problem with OSKM is the induction of genomic instability and tumor formation especially by c-Myc and, to a lesser extent, Klf4." (PMID 26203860, 2015). "KLF4 protein contents were reduced in FBXO22 overexpressed tumor tissues, suggesting an oncogenic role of FBXO22 in vivo." (PMID 26087183, 2015). "Consistently, we found that overexpression of KLF4, an indicated tumor suppressor gene in T-ALL, promoted the SUMOylation and degradation of BCL11B in T-ALL, suggesting that BCL11B acted as an oncogene in T-ALL." (PMID 25644173, 2015). "The suppression of endogenous KLF4 or miR-206 activities abrogated cell survival and in vivo tumor initiation, despite having only subtle effects on MaCSC abundance." (PMID 26053033, 2015). "KLF4, a known target of miR-7, elicits context-dependent oncogenic and tumour suppressive responses and indeed, oncogenesis has been reported as a result of KLF4 suppression by miR-7, as well as the opposite." (PMID 26308064, 2015). "On the other hand, Klf4 can also function as a tumor suppressor as it can antagonize the Wnt pathway resulting in the inhibition of cell proliferation." (PMID 26226504, 2015). "KLF4 has both oncogenic and tumour suppressive roles depending on the tissue in which it is expressed." (PMID 25652398, 2015). "In this study, we demonstrated that microRNA-7 (miR-7) appears to be a novel tumor-suppressor miRNA, which abrogates the stemness of PCSCs and inhibits prostate tumorigenesis by suppressing a key stemness factor KLF4." (PMID 26172296, 2015). "We found that KLF4 was up-regulated in 90% tumor samples (18/20), and miR-7 was down-regulated in 65% tumor samples (13/20)." (PMID 26172296, 2015). "Indicating that the major effect of KLF4 in this setting is restricted to tumor initiation, analysis of the tumor-positive subset revealed little difference in the tumor growth rate between KLF4-depleted cells and the control." (PMID 26053033, 2015). "Consistent with the in vitro data, KLF4 gene transduction inhibited tumor growth compared to the control group as showed by a comparison of tumor volumes." (PMID 26517087, 2015).
tumor (continued). "The role of KLF4 in tumor formation is also very complex, as KLF4 can function as either a tumor suppressor, or tumor promoter, depending upon the cell type and other factors." (PMID 26431332, 2015). "Among the tumor tissues in which miR-7 was suppressed, KLF4 expression was significantly increased than paired adjacent normal tissues." (PMID 26172296, 2015). "Using tumor cells derived from this model as well as human breast cancer cells, suppression of KLF4 and/or KLF5 sensitized HER2-overexpressing cells to lapatinib." (PMID 25789974, 2015). "Depletion of endogenous KLF4 suppressed in vivo tumor initiation by MDA-MB-231 cells in athymic nude mice, yet had little effect on the growth rate of established tumors." (PMID 26053033, 2015). "We found that tumor volumes and weights were significantly increased and cell proliferation was recovered by KLF4 rescue." (PMID 26172296, 2015). "KLF4 is a transcription factor that belongs to the Krüppel family of zinc finger proteins, and exhibits both oncogenic or tumor suppressive functions by interacting with the binding elements on promoters of target genes in different cellular contexts." (PMID 25889839, 2015). "Further mechanistic studies confirmed that KLF4 functions as a tumor suppressor in OSCC development." (PMID 26517087, 2015). "Depending on the type of cancer and genetic context, KLF4 can act as either a tumor suppressor or an oncogene." (PMID 26109433, 2015). "KLF4 acts not only as a tumor suppressor; it also has a dark side in that it acts as an oncogene in OSCC progression." (PMID 26517087, 2015). "Despite the conflicting reporting that indicate that KLF4 plays both tumor suppressing and oncogenic roles in epithelial cancer biology, its function still need to be clarified in the future." (PMID 26517087, 2015). "We are currently assessing other tumor models for KLF4/5-dependent upregulation of anti-apoptotic factors in response to small molecule inhibitors." (PMID 25789974, 2015). "It is also intriguing to note that sustained expression of KLF4 in endothelial cells leads to dysregulation of tumor sprouting angiogenesis and reduced tumor size." (PMID 26075898, 2015). "For example, KLF family proteins have been shown to have either a tumor-promoting (KLF4, KLF6, KLF9, KLF10, KLF11, and KLF17) or a tumor-suppressing (KLF5, KLF12) role by intervening in cell signaling associated with proliferation and/or suppression." (PMID 26320172, 2015). "Kruppel-like factor 4 (KLF4) induces tumorigenesis or suppresses tumor growth in a tissue-dependent manner." (PMID 25644173, 2015). "Both autophagy and KLF4 play important roles in response to stress and function in tumor suppression." (PMID 25944097, 2015). "Along with these roles in normal cells and tissues, KLF4 has important tumor suppressive and oncogenic functions in some malignancies." (PMID 26517087, 2015). "Further studies investigating hypermethylation of the KLF4 5′-untranslated region and microRNA expression will be important to determine how KLF4 expression is regulated in normal and tumor tissues." (PMID 25060774, 2014). "According with the enhanced epithelial cell proliferation and migration resulted from miR-7-mediated KLF4 downregulation, miR-7 overexpression in A549 lung epithelial cells also promoted colony formation in soft agar and tumor formation in nude mice." (PMID 25181544, 2014). "Together, these data indicate that miR-7 promotes tumor progression by targeting KLF4 and indicate that miR-7 acts as an oncomiR in lung epithelial cells." (PMID 25181544, 2014). "Investigating how the microenvironment influences KLF4 expression and thus tumorigenesis, tumor progression, and prognosis, will be important in future studies." (PMID 25060774, 2014). "Krüppel-like factor 4 (KLF4) plays an important role in cell proliferation and differentiation, and it can function as a tumor suppressor or an oncoprotein, depending on tissue type." (PMID 24897024, 2014).